ARTN (artemin)
Description:
Growth factor that supports the survival of sensory and sympathetic peripheral neurons in culture and also supports the survival of dopaminergic neurons of the ventral mid-brain. Acts by binding to its coreceptor, GFRA3, leading to autophosphorylation and activation of the RET receptor. Strong attractant of gut hematopoietic cells thus promoting the formation Peyer's patch-like structures, a major component of the gut-associated lymphoid tissue (By similarity).
Synonyms: EVN; NBN; ENOVIN; ART
Tractability: Antibody: UniProt places it where antibodies can reach, with high confidence; its Gene Ontology location is reachable by antibodies, with high confidence; UniProt predicts a signal peptide or a membrane-spanning region.
Gene: Protein-coding gene on chromosome 1 (43,933,320 to 43,937,244, forward strand). Ensembl gene ENSG00000117407.
Subcellular location: Secreted
Pathways (Reactome):
Developmental Biology: NCAM1 interactions; RET signaling
Signal Transduction: RAF/MAP kinase cascade
Gene Ontology:
Molecular function: growth factor activity; protein binding; signaling receptor binding; glial cell-derived neurotrophic factor receptor binding; receptor tyrosine kinase binding
Biological process: glial cell-derived neurotrophic factor receptor signaling pathway; neuroblast proliferation; neuron projection development; signal transduction; lymphocyte migration into lymphoid organs; nervous system development; peripheral nervous system development; Peyer's patch morphogenesis
Cellular component: extracellular region
Genetic constraint (gnomAD): Loss-of-function variants: 5 observed, 8.7 expected, observed/expected ratio (o/e) 0.57, 90% interval 0.3 to 1.21. That is too few expected variants to judge how well the gene tolerates losing a copy. Missense variants: 262 observed, 208.85 expected, observed/expected ratio (o/e) 1.25, 90% interval 1.13 to 1.39. Synonymous variants: 152 observed, 106.33 expected, observed/expected ratio (o/e) 1.43, 90% interval 1.25 to 1.63.
Homologues: Orthologues: macaque ARTN (95% identical), chimpanzee ARTN (92% identical), pig ARTN (83% identical), rabbit ARTN (81% identical), rat Artn (80% identical), mouse Artn (77% identical), guinea pig ARTN (76% identical), zebrafish artna (22% identical). Paralogues in human: NRTN (30% identical), PSPN (28% identical), GDNF (22% identical).
Diseases named in the same sentence as ARTN in open-access papers:
ARTN is named in the same sentence as 81 diseases in open-access papers, as found by Europe PMC text mining. Sharing a sentence is not in itself a finding about the gene and the disease. The quoted sentences say what the papers report.
breast carcinoma (15 papers, 2011 to 2025). "In addition, the expression levels of ARTN and its receptors have been observed to be upregulated in breast cancer and significantly associated with disease progression." (PMID 25120606, 2014). "Other studies have suggested that ARTN is regulated by estrogen and mediates estrogen resistance in breast cancer." (PMID 39091505, 2024). "Previous research indicated that ARTN enhances metastasis and invasiveness in breast cancer, pancreatic cancer, endometrial cancer, and non-small cell lung cancer." (PMID 36471885, 2022). "ARTN can enhance oncogenicity, tumor growth, and invasiveness in human malignancies, such as breast cancer, pancreatic carcinoma, endometrial carcinoma, hepatocellular carcinoma, and non-small-cell lung carcinoma." (PMID 36471885, 2022). "ARTN also plays a role in mammary carcinoma progression and metastasis via enhancing endothelial cell proliferation, migration, invasion and Matrigel tube formation." (PMID 32573073, 2020). "Using xenograft experiments, mammary carcinoma cells overexpressing ARTN were found to induce tumour formation with increased microvessel density, accompanied by increased VEGF‐A expression." (PMID 32573073, 2020). "Emerging evidence indicates that ARTN is involved in the tumorigenesis, tumour metastasis and therapeutic resistance to cancers, such as mammary carcinoma, pancreatic adenocarcinoma and acute myeloid leukaemia." (PMID 32573073, 2020). "Genetic manipulation studies indicate that upregulation of ARTN increases the resistance of mammary carcinoma cells to trastuzumab; silencing of ARTN enhanced the efficacy of trastuzumab." (PMID 32573073, 2020). "A recent report indicated hypoxia induced CSC expansion is mediated through AKT/β-catenin signaling in breast cancer, which is consistent with our conclusion that hypoxia responsive ARTN promoted HCC CSC properties via activation of AKT." (PMID 26675549, 2016). "It has also been demonstrated that ARTN promotion of the CSC population in ER- mammary carcinoma cells is equally efficacious in RET positive or RET negative cells." (PMID 26675549, 2016). "Recent studies have demonstrated a pivotal functional role of ARTN in acquired resistance to multiple therapeutic approaches utilized in mammary carcinoma." (PMID 26675549, 2016). "It has been also reported that ARTN confers chemo- and radio-resistance upon mammary carcinoma cells by promoting TWIST1-BCL-2-dependent CSC-like behavior." (PMID 26675549, 2016). "Their prognostic significance combined with ARTN expression was also investigated in mammary carcinoma." (PMID 23351331, 2013). "In mammary carcinoma (MC), increased expression of ARTN has been observed compared to normal tissue and expression of ARTN in MC predicted residual disease after chemotherapy, metastasis, relapse, and death." (PMID 23351331, 2013). "ARTN has previously been demonstrated to be involved in progression of various carcinomas including mammary carcinoma." (PMID 23185544, 2012). "We determined the effects of ARTN secreted by these two mammary carcinoma cell lines on HMEC-1 monolayer proliferation, migration, invasion and tube formation." (PMID 23185544, 2012). "The neurotrophic factor ARTEMIN (ARTN) has been reported to possess a role in mammary carcinoma progression and metastasis." (PMID 23185544, 2012). "We report herein that ARTN secreted from mammary carcinoma cells promotes tumor angiogenesis which is mediated in part by enhanced VEGF-A expression." (PMID 23185544, 2012). "TWIST1 signalling has been reported to promote VEGF-A expression in mammary carcinoma cells and we have previously demonstrated that ARTN increased TWIST1 expression to modulate ARTN stimulated oncogenicity." (PMID 23185544, 2012). "Increased expression of ARTN has been identified in several human cancers including breast cancer, pancreatic cancer, thyroid carcinoma and endometrial carcinoma." (PMID 21453483, 2011).
breast carcinoma (continued). "We modulated the expression of ARTN in two ER- (mesenchymal/claudin-low) mammary carcinoma cell lines (BT549 and MDA-MB-231) by forced expression or small interfering RNA (siRNA) mediated depletion." (PMID 22060274, 2011). "To further confirm the correlation of expression between TWIST1 and ARTN in mammary carcinoma, we compared the relationship by Spearman's rank correlation coefficient and found a significant positive value (Spearman correlation: rs = 0.21, P = 0.03)." (PMID 22060274, 2011). "ARTN expression has previously been correlated with poorer survival outcome in mammary carcinoma overall and in ER+MC patients treated with tamoxifen." (PMID 22060274, 2011). "Moreover, BCL-2 was reported to be regulated by ARTN and contributed to trastuzumab resistance of human breast cancer." (PMID 33623790, 2021). "The expression of ARTN and receptor subunits may predict the progression and outcome of mammary carcinoma subtypes." (PMID 32573073, 2020). "ARTN expression induced by oestrogen in mammary carcinoma is involved in resistance to tamoxifen therapy, whereas antagonism of ARTN appears to enhance the efficacy of antioestrogens and may represent an adjunctive therapeutic approach." (PMID 32573073, 2020). "Furthermore, co-expression of ARTN with its receptors has been found to produce synergistic increases in the odds ratio for survival in patients with breast cancer." (PMID 25120606, 2014). "However, the prognostic significance of upstream ligand binding components, potentially mediating ARTN oncogenicity in mammary carcinoma, remain to be determined." (PMID 23351331, 2013). "The expression of GFRα1 and/or GFRα3, especially when combined with ARTN expression, may be useful predictors of disease progression and outcome in specific subtypes of mammary carcinoma." (PMID 23351331, 2013). "Thus, apart from direct actions on endothelial cells, ARTN also co-ordinately regulates a pro-angiogenic programme of gene expression from mammary carcinoma cells." (PMID 23185544, 2012). "ARTN may therefore stimulate a co-ordinated programme of gene expression promoting oncogenicity of mammary carcinoma and progression of the clinical disease." (PMID 23185544, 2012). "ARTEMIN (ARTN) is an estrogen regulated growth factor, the expression of which promotes resistance to antiestrogen therapies and predicts poorer survival outcome of patients with estrogen receptor (ER) positive mammary carcinoma (ER+MC) treated with tamoxifen." (PMID 22060274, 2011). "Importantly, depletion or inhibition of ARTN partially restores tamoxifen sensitivity in tamoxifen-resistant mammary carcinoma cells." (PMID 22060274, 2011). "For example, it has been demonstrated that the expression of ARTN is significantly increased in breast cancer tissues compared with normal breast tissues, and that high expression of ARTN is positively correlated with high tumor stage and poor survival in breast cancer." (PMID 25120606, 2014). "Thus, ARTN secreted by mammary carcinoma cells may possess an important role in modulating endothelial cell behaviour." (PMID 23185544, 2012). "In addition, depletion of ARTN can inhibit breast cancer metastasis in vivo." (PMID 21453483, 2011). "Consistent with our findings, ARTN stimulated AKT signaling and accelerated the migration and invasion of mammary carcinoma and pancreatic adenocarcinoma cancer cells." (PMID 36471885, 2022). "We determined the mRNA and protein expression of three proteins demonstrated to bind ARTN, namely GFRα1, GFRα3 and Syndecan-3 (SDC3), in benign breast disease and mammary carcinoma by in situ hybridization and immunohistochemistry, respectively." (PMID 23351331, 2013). "To determine the involvement of ARTN secreted from mammary carcinoma cells on endothelial cell angiogenic behaviour we transiently depleted endogenous ARTN expression in MCF-7 and MDA-MB-231 cells by use of siRNA to ARTN." (PMID 23185544, 2012).
breast carcinoma (continued). "We initially choose two different wild type human mammary carcinoma cell lines, MCF-7 and MDA-MB-231 with different endogenous expression levels of ARTN." (PMID 23185544, 2012). "ARTN regulated TWIST1 expression in ER-MC cells and ARTN expression was significantly correlated to TWIST1 expression in a panel of mammary carcinoma cell lines and in a cohort of patients with ER-MC." (PMID 22060274, 2011). "Both ARTN and TWIST1 mRNA were ubiquitously expressed across different mammary carcinoma cell lines and increased ARTN and TWIST1 mRNA expression correlated with a more invasive cell phenotype." (PMID 22060274, 2011). "In these cell lines, it has been consistently demonstrated that treatment with estradiol (E2) induces transcription of multiple RET signaling system components, including RET, GFRA1, and ARTN, suggesting a regulatory mechanism for RET’s functions in breast cancer." (PMID 36918928, 2023). "Through expression of twist family BHLH transcription factor 1 (TWIST1), ARTN increases metastasis in patients with estrogen receptor (ER)-negative mammary cancer (ER-MC)." (PMID 36471885, 2022). "ARTN was found to promote metastasis and poor survival outcome in patients with estrogen receptor (ER) negative mammary carcinoma (ER‐MC) via its cooperation with twist family BHLH transcription factor 1 (TWIST1)." (PMID 32573073, 2020). "ARTN activation of AKT was previously demonstrated to promote the expression of BCL-2 and TWIST1 resulting in enhanced oncogenicity and an increased CSC population in breast cancer." (PMID 26675549, 2016). "Interestingly, ARTN also promotes the expression of other secreted proteins, such as TFF3 which also promotes the oncogenic behaviour of mammary carcinoma cells and possesses angiogenic activity." (PMID 23185544, 2012). "Furthermore, we have demonstrated that ARTN secreted by ER-MC cells also regulates endothelial cell function, at least in part by increasing the expression of VEGF-A from mammary carcinoma cells." (PMID 23185544, 2012). "ARTN and TWIST1 synergize to produce a worse outcome in ER-MC and combined inhibition of ARTN and phosphatidylinositol 3-kinase/protein kinase B (PI3K/AKT) may therefore provide a novel therapeutic strategy in this subtype of mammary carcinoma." (PMID 22060274, 2011). "Combined inhibition of ARTN and PI3K/AKT/TWIST1 could therefore represent a valuable therapeutic approach in ER-MC mammary carcinoma." (PMID 22060274, 2011). "ARTN and TWIST1 may therefore functionally synergize in aspects of mammary carcinoma cell behavior other than EMT and metastasis reported herein." (PMID 22060274, 2011). "Correlation between ARTEMIN (ARTN) and TWIST1 expression in estrogen receptor (ER) negative mammary carcinoma (ER-MC)." (PMID 22060274, 2011). "Co-expression of ARTN with either GFRα1 or GFRα3, but not SDC3, produced synergistic increases in the odds ratio for both relapse-free and overall survival in patients with mammary carcinoma." (PMID 23351331, 2013). "Increased ARTN expression in mammary carcinoma promotes metastasis, radio-resistance (manuscript submitted), chemo-resistance, endocrine resistance and also enhances CSC like activity in estrogen receptor negative mammary carcinoma (ER-MC) (manuscript submitted)." (PMID 23185544, 2012).
hepatocellular carcinoma (9 papers, 2016 to 2025). A malignant tumor that arises from hepatocytes. "Recently, it was discovered that elevated serum ARTN in hepatocellular carcinoma patients is associated with a poor prognosis." (PMID 36471885, 2022). "For example, CD45−Ter119+CD71+ erythroblast-like cells in the spleens of patients with hepatocellular carcinoma and in a corresponding disease mouse model were shown to facilitate cancer cell metastasis via the secretion of artemin." (PMID 41392984, 2025). "Artemin-expressing CD45− EPCs were also detected in the spleens of patients with hepatocellular carcinoma (HCC) and pancreatic ductal adenocarcinoma (PDAC), which suggests their role in cancer patients." (PMID 33669537, 2021). "Given that it has also recently been described that ARTN is also produced by splenic Ter cells, and secreted to serum to promote hepatocellular carcinoma progression, then examination of tumor ARTN expression will potentially underestimate the full contribution of ARTN to relapse and survival." (PMID 34422665, 2021). "Furthermore, a recent study has indicated that splenic Ter-cells also secrete ARTN to promote hepatocellular carcinoma progression." (PMID 34422665, 2021). "GFLs are also linked with hepatocellular carcinoma (HCC), as high expression of GFRα3 or phosphorylation of Ret in HCC tissues and an increase of ARTN in the serum correlate with poor prognosis in HCC patients." (PMID 32252363, 2020). "In hepatocellular carcinoma (HCC), ARTN was found to promote the growth and progression of HCC based on increased clinical tissue expression, increased tumour size, increased relapse and shorter survival time." (PMID 32573073, 2020). "ARTN protein expression in hepatocellular carcinoma samples and the corresponding adjacent non-tumorous tissues was also specifically examined by IHC staining." (PMID 26675549, 2016). "Herein, we show that Artemin (ARTN), a member of the glial cell derived neurotrophic factor family of ligands, is a hypoxia-responsive factor and is essential for hypoxia-induced CSC expansion in hepatocellular carcinoma (HCC)." (PMID 26675549, 2016).
osteoarthritis (8 papers, 2020 to 2026). A noninflammatory degenerative joint disease occurring chiefly in older persons, characterized by degeneration of the articular cartilage, hypertrophy of bone at the margins and changes in the synovial membrane. "Conversely, blocking artemin signaling in rat model of osteoarthritis with neutralizing antibodies prevents pain and reverses nociceptive neuron hypersensitivity, highlighting its potential as a therapeutic target." (PMID 40705105, 2025). "ARTN, a neurotrophic factor, influences sensory neuron function and osteoarthritis pain perception and correlates with pain indexes and cognitive impairment in LC patients with ME/CFS." (PMID 41205594, 2025). "Indeed, in animal models of inflammatory and osteoarthritis pain, blocking artemin signaling with neutralizing antibodies reduces nociceptive neuron sensitization and alleviates pain." (PMID 40705105, 2025). "Some studies suggest that ARTN/GFRα3 signaling is involved in the pathogenesis of bone pain, and inhibition of this process could be used to treat pain in osteoarthritis (OA) when pathological features are present in the subchondral bone." (PMID 39091505, 2024).
pancreatic cancer (8 papers, 2011 to 2023). "In pancreatic ductal adenocarcinoma, ARTN has been reported to be highly expressed compared with normal pancreases, and stimulates the invasiveness of pancreatic cancer cells." (PMID 25120606, 2014). "Interestingly, over the past few years artemin has been identified as a significant player in the enhancement of oncogenicity of various other tumors besides pancreatic cancers." (PMID 22891163, 2012). "Additionally, the neurotrophic factor artemin promotes pancreatic cancer invasion." (PMID 37566075, 2023). "Finally, the authors showed that tissue extracts from pancreatic cancer as well as from the surrounding normal pancreatic tissue stimulate neuritogenesis in myenteric plexus-cultures, an effect which was abrogated by depletion of artemin and/or NGF." (PMID 33142779, 2020). "For instance, GDNF and other members of the GDNF family (artemin, NRTN and persephin) were shown to play important cancer promoting roles in pancreatic cancer." (PMID 33142779, 2020). "Consistently, ARTN and CXC chemokine receptor 4 (CXCR4) were found to be overexpressed in pancreatic cancer tissues, and the migration and invasion of pancreatic cancer cells appears to be promoted by Akt and ERK 1/2/NF‐κB signalling and the stromal cell‐derived factor 1α (SDF‐1α)/CXCR4 axis." (PMID 32573073, 2020).